SIRPG (signal regulatory protein gamma)
Diseases named in the same sentence as SIRPG in open-access papers (continued):
Sharing a sentence is not in itself a finding about the gene and the disease.
tumor (18 papers, 2016 to 2025). "In this study, we found that high SIRPG expression was associated with an inflamed tumor immune microenvironment and a better response to PD-1 blockade." (PMID 38833156, 2024). "We further assessed the impact of the SIRPγ/YAP axis on tumor metastasis, a property often associated with CSLCs." (PMID 35229723, 2022). "Furthermore, CEBPE and SIRPG mRNA expression correlates with an anti-tumor microenvironment transcriptional profile and is linked to a “hot” immune infiltration profile in HNSC patients." (PMID 41048343, 2025). "Therefore, potential blockade of SIRPγ may result in the inhibition of tumor-associated T cells, which would reduce the therapeutic effect of SIRPα targeting antibodies." (PMID 40408355, 2025). "However, the associations between SIRPG expression and tumor immune microenvironment phenotypes or T cell mediated-adaptive antitumor immunity, and its predictive value for PD-1 blockade remain largely unknown." (PMID 38833156, 2024). "SIRPG high-expressed tumors exhibited immunologically “hot” tumor immune microenvironment phenotype, with more tumor-infiltrating cells of both adaptive and innate immune systems such as T, B, NK cells, and DCs." (PMID 38833156, 2024). "Among all cell subtypes, we found that SIRPG was mainly expressed on T cells, followed by tumor cells." (PMID 38833156, 2024). "In this study, we systematically depicted the pan-cancer expression profiles of SIRPG among 33 cancer subtypes from TCGA database and characterized the relevance between SIRPG expression and tumor immune landscape." (PMID 38833156, 2024). "Based on the important roles of SIRPG in both tumor and immune cells, we evaluated the SIRPG-related expression traits, enrichment pathways, and immune infiltration characteristics in both LUAD and LUSC." (PMID 38833156, 2024). "Firstly, we analyzed the distinct expression levels of SIRPG between normal and tumor tissues using transcriptomic datasets from the TCGA program." (PMID 38833156, 2024). "To further survey the significant impact of SIRPG expression on tumor immune phenotypes, we compared the transcriptome characteristics between lung tumors with high and low SIRPG expression." (PMID 38833156, 2024). "In conclusion, the current study reported that SIRPG expression positively correlated with an “hot” tumor immune phenotype and favorable response to PD-1 blockade." (PMID 38833156, 2024). "As in the case of downmodulation by shRNA, expression of CD47 in anti-SIRPγ mAb–treated tumor cells was restored by exposure to IL-1β and GM-CSF." (PMID 35229723, 2022). "The results showed that the anti-SIRPγ blocking antibody decreased tumor growth compared with anti-IgG treatment." (PMID 35229723, 2022). "We observed that the SIRPγ mAb treatment markedly inhibited tumor growth in vivo in a dose-dependent manner, as determined by reduced tumor size and weight." (PMID 35229723, 2022). "Although earlier studies have not revealed expression and functions of SIRPγ in any cancer types, the discovery of increased SIRPG mRNA in LUAD CSLCs led us to search for a possible role in tumor progression." (PMID 35229723, 2022). "In accordance with this idea, we observed that SIRPγ overexpression promoted growth of human LUAD tumors in the xenograft model, while knockdown of YAP inhibited tumor growth and abrogated the tumor-promoting effect upon SIRPγ overexpression." (PMID 35229723, 2022). "Beginning 6 days after tumor cell injection, the mice received 4 doses of the anti-SIRPγ mAb, administered every second day, and tumors were assessed on day 21 after inoculation." (PMID 35229723, 2022). "In human lung cancer, there are many important anti-tumor costimulatory molecules such as SIRPG and KIR2DL4 on the surface of TRM cells, which help the CTLs kill tumor cells." (PMID 34707601, 2021).
tumor (continued). "We found that LGALS9_CD44, MIF_TNFRSF14, CD47_SIRPG, MDK_LRP1 and LGALS9_HAVCR2, CD74_COPA, C3_C3AR1, ANXA1_FPR3 interactions were upregulated in both ductal-tumor and malignant cells versus ductal-normal." (PMID 35087839, 2021). "Therefore, in terms of inhibiting tumor cells themselves and enhancing anti-tumor immunity, SIRPG serves as an important treatment target." (PMID 38833156, 2024). "This phenomenon suggested that a hot tumor immune microenvironment might contribute to the upregulation expression of SIRPG, which in turn led to the exhaustion of T cells to avoid excessive immune activation." (PMID 38833156, 2024). "SIRPγ promoted tumor growth and metastasis in vivo through YAP signaling." (PMID 35229723, 2022). "Notably, depletion of YAP by shRNA knockdown abrogated the tumor metastasis and increased lung weight promoted by SIRPγ overexpression and correspondingly improved survival of the recipient mice." (PMID 35229723, 2022). "SIRPγ-neutralizing antibody targets both CSLCs and immune evasion to inhibit tumor growth in vivo." (PMID 35229723, 2022). "Importantly, we showed that targeting SIRPγ with LSB2.20 also reduced in vivo tumor growth of a LUAD patient–derived xenograft (PDX) model." (PMID 35229723, 2022). "The effects of SIRPγ on both promoting the intrinsic properties of CSLCs and on the capacity of bulk tumor cells to evade innate immune surveillance imply that the protein could be a significant therapeutic target." (PMID 35229723, 2022). "In the in vivo xenograft model, we observed that knockdown of SIRPγ inhibited tumor growth." (PMID 35229723, 2022). "To investigate whether the functional role of the SIRPγ/YAP axis in promoting tumor development results partly from inhibition of phagocytosis, we utilized GFP-labeled A549 cells to assess their engulfment by macrophages in vivo." (PMID 35229723, 2022). "Our study implies that SIRPγ could be a valuable target for therapy of LUAD with the potential to both directly attack tumor- and metastasis-initiating CSLCs and to inhibit an important mechanism of immune evasion." (PMID 35229723, 2022). "We concluded that SIRPγ acts through YAP signaling to promote tumor growth." (PMID 35229723, 2022). "Importantly, F05 does not bind SIRPγ on human T cells, which mitigates the risk of potential inhibition of tumor infiltrating lymphocytes (TIL) or other activated T cells systemically." (PMID 40408355, 2025). "However, the relationship between SIRPG expression and tumor microenvironment and whether SIRPG expression impacts response to immune checkpoint inhibitors remains elusive." (PMID 38833156, 2024). "The high expression of SIRPG might be a consequence of a hot tumor microenvironment, which subsequently promoted the dysfunction of T cells to avoid excessive immune activation and attenuated anti-tumor immunity." (PMID 38833156, 2024). "Blockade of SIRPG using its monoclonal antibody could significantly suppress tumor growth in vivo." (PMID 38833156, 2024). "We then identified the relationship between SIRPG expression and the expression levels of MHC, immunostimulatory, immunoinhibitory, and cytotoxic molecules in tumor tissues based on bulk RNA-seq data." (PMID 38833156, 2024). "This study aimed to investigate the relationship between signal regulatory protein gamma (SIRPG) and tumor immune microenvironment phenotypes or T cell mediated-adaptive antitumor immunity, and its predictive value for response to PD-1 blockade in cancers." (PMID 38833156, 2024). "In TME (Tumour Micro Environment), the role of TYROBP and SIRPG in regulating NK cells, leukocyte adhesion, and modulating immune cells is well established." (PMID 37091785, 2023). "We found that knockdown of either SIRPγ or YAP in A549 and H1975 cells markedly inhibited the tumor signal intensity and the number of tumor nodules formed in the lungs of recipient mice and correlated with reduced lung weight." (PMID 35229723, 2022).
tumor (continued). "Tumor cells could use the “Don’t eat me” signal, such as CD47 34, SIRPG PD-136 and CD24 37, to escape recognition and phagocytosis by macrophages, which were significant contributors to the recurrence, metastasis, and therapeutic resistance of various cancers." (PMID 40682115, 2025). "The function of both SIRPβ and SIRPγ are not well described; however, initial characterization of SIRPγ has revealed a role in promoting the chronic activation and migration of T-cells and promoting stem-like characteristics of tumor cells." (PMID 40408355, 2025). "Because of the important role of intra-tumoral T cells in eliminating tumor cells, and the potential for reduction of T-cell function by engagement of SIRPγ, the lack of binding of F05 to human T cells provides a distinct advantage over other available agents." (PMID 40408355, 2025). "Secondly, the interplay between SIRPG expression and the tumor microenvironment was not fully elucidated and warrants additional exploration." (PMID 38833156, 2024). "Here the authors engineer anti-EGFRvIII CAR T cells to secrete an optimized SIRPγ-derived CD47 blocker, showing that combining CAR T cell effector functions with enhanced macrophage-mediated tumor cell phagocytosis improves anti-tumor efficacy in preclinical models." (PMID 39521782, 2024). "Notably, SIRPγ targeting with genetic SIRPγ knockdown or a SIRPγ-neutralizing antibody inhibited CSLC phenotypes and elicited phagocytosis that suppressed tumor growth in vivo." (PMID 35229723, 2022). "SIRPγ bridged MST1 and PP2A to facilitate MST1 dephosphorylation, resulting in Hippo/YAP activation and leading to cytokine release by CSLCs, which stimulated CD47 expression in LUAD cells and consequently inhibited tumor cell phagocytosis." (PMID 35229723, 2022). "Yet, a direct role of SIRPG tumor cell maintenance or redox process is not evident, making its appearance in our most correlating genes interesting for future studies." (PMID 35063803, 2022). "CEBPE and SIRPG mRNA expression levels were higher in tumor than in non-tumor samples." (PMID 41048343, 2025). "When equal numbers of A549 cells (1 × 106) were inoculated into NDG mice reconstituted with or without PBMCs for tumorigenesis assays, targeting SIRPγ with LSB2.20 resulted in better efficacy in suppressing tumor growth in humanized NDG mice than in NDG mice without PBMC reconstitution." (PMID 35229723, 2022).
cancer (5 papers, 2022 to 2026). A tumor composed of atypical neoplastic, often pleomorphic cells that invade other tissues. "High SIRPG expression is associated with an inflamed immune phenotype in cancers and favorable response to PD-1 blockade, suggesting it would be a promising predictive biomarker for PD-1 blockade and novel immunotherapeutic target." (PMID 38833156, 2024). "The increase in CD47 by exogenously supplied IL-1β and GM-CSF also sufficed to overcome the enhanced sensitivity of cancer cells to phagocytosis caused by knockdown of SIRPγ." (PMID 35229723, 2022). "Importantly, adding back IL-1β and GM-CSF to SIRPγ-deficient cancer cells rescued CD47 expression, leading to inhibition of phagocytosis by macrophages and restoration of tumorigenesis." (PMID 35229723, 2022). "This review compares the structure, ligand interactions, and signaling mechanisms of SIRPα, SIRPβ, and SIRPγ, summarizes their roles in cancer, autoimmunity and neurodegeneration, and surveys therapeutic strategies that target the CD47-SIRPα axis." (PMID 41822520, 2026). "Consistently in multiple TCGA cancer cohorts, most cancer types with high SIRPG expression level had similar disease-free survival (DFS) and OS after adjustment for potential confounding factors such as FDR." (PMID 38833156, 2024). "Taken together, these results suggested that SIRPG plays a significant role in T cell mediated-adaptive antitumor immunity and would be a promising predictive biomarker for PD-1 blockade in cancers and a novel immunotherapeutic target." (PMID 38833156, 2024). "Together these findings revealed that lung tumors with high SIRPG expression had inflamed immune phenotypes, indicating the significant role of SIRPG in cancer-immunity cycle of lung tumors." (PMID 38833156, 2024). "We then conducted experiments to define the role of SIRPγ in the growth of organoids from NSCLC patient–derived tumors and found that SIRPγ or YAP overexpression promoted cancer organoid growth, while SIRPγ or YAP knockdown reduced it." (PMID 35229723, 2022). "Conversely, CD47 overexpression decreased the sensitivity of cancer cells to phagocytosis, leading to reversal of the increased phagocytosis of the SIRPγ-knockdown cancer cells by macrophages." (PMID 35229723, 2022). "Although SIRPG mRNA expression was much higher in immune cells than A549 and H1975, its mRNA and protein expression was highly enriched in cancer spheres compared with the monolayer culture." (PMID 35229723, 2022). "Our study therefore highlights the critical role of SIRPγ in YAP signaling activation that leads to promoting cancer progression and metastasis." (PMID 35229723, 2022). "By contrast, CD47 was among a set of genes showing increased expression in SIRPγhi A549 and H1975 cells compared with SIRPγlo/– cells selected by flow cytometry and SIRPγ-overexpressing cancer cells." (PMID 35229723, 2022). "Of note, we found that YAP knockdown compromised the promoting effect of SIRPγ on cancer organoid growth." (PMID 35229723, 2022). "We observed that overexpression of YAP rescued the defect in the expression of IL-1β and GM-CSF cytokines and CD47 expression in SIRPγ-knockdown cancer cells, and also reversed heightened phagocytosis of the SIRPγ-knockdown cancer cells by macrophages." (PMID 35229723, 2022). "Also, CD274 (PD-L1) showed positive association with SIRPG, whereas RATE1E, CD276 and VEGFA expression seemed to be negatively correlated with SIRPG expression in a subset of TCGA cancers." (PMID 38833156, 2024). "Consistently across most cancer types with high SIRPG expression (vs. low SIRPG expression), we observed remarkable increase in abundance of T, B, NK, T follicular helper cells, and M1 macrophages, and significant decrease in abundance of neutrophils, M2 macrophages and MDSC." (PMID 38833156, 2024). "In light of our observation that SIRPγ is critical for CD47 expression in CSLCs, we asked whether SIRPγ expression influences phagocytosis of the cancer cells by macrophages." (PMID 35229723, 2022).
cancer (continued). "Moreover, depletion of IL-1β or GM-CSF by shRNA knockdown abrogated the effect of SIRPγ overexpression on reducing sensitivity of cancer cells to phagocytosis." (PMID 35229723, 2022). "Furthermore, overexpression of YAP compromised the increased phagocytosis in SIRPγ-knockdown cancer cells." (PMID 35229723, 2022). "SIRPγ helps cancer cells to escape from phagocytosis by macrophages through YAP signaling." (PMID 35229723, 2022). "Our study reveals the expression and functional role of SIRPγ in cancer cells." (PMID 35229723, 2022). "Overexpression of YAP rescued the defect in the expression of IL-1β and GM-CSF cytokines and CD47 expression in SIRPγ-knockdown cancer cells, supporting the notion that SIRPγ acts through the Hippo/YAP pathway to regulate the expression of IL-1β, GM-CSF, and CD47." (PMID 35229723, 2022). "Thus, our study not only opens up a promising avenue for studying SIRPγ in cancer, but also offers a potential target for NSCLC treatment." (PMID 35229723, 2022). "To determine whether SIRPγ is likely a general CSLC marker, we conducted qRT-PCR and Western blot analyses in a variety of cancer cell lines with distinct cancer cell origins and found that SIRPG mRNA and protein expression was also enriched in cancer spheres compared with the monolayer culture." (PMID 35229723, 2022). "Precipitation of cancer cell lysates with an antibody against PP2A also enriched for precipitated MST1 and SIRPγ." (PMID 35229723, 2022). "Besides, significantly positive correlations were observed between gene expression of SIRPG and MHC, immunostimulatory, and other immunoinhibitory molecules in most cancers." (PMID 38833156, 2024). "Cancers with high SIRPG expression had significantly higher abundance of CD8+ T cells, especially central memory CD8+ T cells than those with low SIRPG expression in various cancers." (PMID 38833156, 2024). "Thus, targeting SIRPγ not only represents an effective strategy to abrogate YAP-dependent signaling, but also serves as a CSLC- and immune-targeting strategy to block cancer progression and metastasis." (PMID 35229723, 2022). "SIRPγ was previously shown to be expressed primarily in T cells and NK cells, but its expression and functional roles in cancer cells have never been reported to the best of our knowledge." (PMID 35229723, 2022). "We would like to point out that targeting SIRPγ with either 2 or 4 μg/mL LSB2.20 could markedly inhibit YAP signaling, cancer sphere formation, and elicit increased phagocytosis." (PMID 35229723, 2022). "Importantly, we showed that SIRPγ not only serves as a CSLC marker of NSCLC by using numerous in vitro and in vivo approaches, but also plays a key role in maintaining CSLCs of NSCLC, in turn promoting cancer progression and metastasis of NSCLC in animal models." (PMID 35229723, 2022). "SIRPγ serves as a negative upstream regulator of the MST1/LATS1 axis to promote YAP activation and cancer organoid growth." (PMID 35229723, 2022). "Because we observed detectable surface SIRPγ protein expression in less than 10% of A549 and H1975 cells cultured under standard conditions, comprising the CSLC populations, we were puzzled to account for how SIRPγ might control CD47 expression by the large majority of (non-stem) cancer cells." (PMID 35229723, 2022).
SIRPG also shares sentences with these, for which no sentence is quoted: bladder cancer (1 paper); breast carcinoma (1); COVID-19 (1); diabetic retinopathy (1); endometrial carcinoma (1); glioblastoma (1); head and neck squamous cell carcinoma (1); immune disorders (1); lung squamous cell carcinoma (1); lymphopenia (1); myopia (1); preeclampsia (1); rheumatoid arthritis (1); senile cataract (1); skin cutaneous melanoma (1).